CLCN2 (chloride voltage-gated channel 2)
Description:
Voltage-gated and osmosensitive chloride channel. Forms a homodimeric channel where each subunit has its own ion conduction pathway. Conducts double-barreled currents controlled by two types of gates, two fast glutamate gates that control each subunit independently and a slow common gate that opens and shuts off both subunits simultaneously. Displays inward rectification currents activated upon membrane hyperpolarization and extracellular hypotonicity. Contributes to chloride conductance involved in neuron excitability. In hippocampal neurons, generates a significant part of resting membrane conductance and provides an additional chloride efflux pathway to prevent chloride accumulation in dendrites upon GABA receptor activation. In glia, associates with the auxiliary subunit HEPACAM/GlialCAM at astrocytic processes and myelinated fiber tracts where it may regulate transcellular chloride flux buffering extracellular chloride and potassium concentrations. Regulates aldosterone production in adrenal glands. The opening of CLCN2 channels at hyperpolarized membrane potentials in the glomerulosa causes cell membrane depolarization, activation of voltage-gated calcium channels and increased expression of aldosterone synthase, the rate-limiting enzyme for aldosterone biosynthesis. Contributes to chloride conductance in retinal pigment epithelium involved in phagocytosis of shed photoreceptor outer segments and photoreceptor renewal. Conducts chloride currents at the basolateral membrane of epithelial cells with a role in chloride reabsorption rather than secretion (By similarity). Permeable to small monovalent anions with chloride > thiocyanate > bromide > nitrate > iodide ion selectivity (By similarity).
Synonyms: ClC-2; CLC2; EJM6; CIC-2; ECA2; ECA3; EGI11; EGI3; EGMA; EJM8; FHA2; FHII; HALD2; LKPAT
Tractability: Small molecule: an approved drug acts on it; a structure with a bound ligand is known; it belongs to a druggable protein family. Antibody: UniProt places it where antibodies can reach, with high confidence; its Gene Ontology location is reachable by antibodies, with high confidence; UniProt predicts a signal peptide or a membrane-spanning region. PROTAC: ubiquitination databases record sites on it.
Target class: Chloride channel; ClC chloride channel; Other ion channel; Ion channel
Chemical probes: AK-42
Gene: Protein-coding gene on chromosome 3 (184,346,185 to 184,363,274, reverse strand). Ensembl gene ENSG00000114859.
Subcellular location: Cell membrane; Basolateral cell membrane; Cell projection, dendritic spine membrane; Cell projection, axon
Subcellular location (Human Protein Atlas): Cytosol
Pathways (Reactome):
Transport of small molecules: Stimuli-sensing channels
Gene Ontology:
Molecular function: chloride channel regulator activity; voltage-gated chloride channel activity; chloride transmembrane transporter activity; voltage-gated monoatomic anion channel activity; volume-sensitive chloride channel activity
Biological process: phagocytosis, engulfment; regulation of aldosterone biosynthetic process; chloride transport; cellular hypotonic response; chloride transmembrane transport; lung development; monoatomic anion transmembrane transport; positive regulation of oligodendrocyte differentiation; regulation of membrane depolarization during action potential; regulation of resting membrane potential; stabilization of membrane potential; transmembrane transport
Cellular component: astrocyte end-foot; basolateral plasma membrane; myelin sheath; plasma membrane; axon; axon initial segment; dendrite; dendritic spine membrane; membrane; perikaryon
Genetic constraint (gnomAD): Loss-of-function variants: 72 observed, 111.46 expected, observed/expected ratio (o/e) 0.65, 90% interval 0.53 to 0.79. The upper end of that interval is the gene's LOEUF score, 0.79, which puts it in group 3 of 6, group 1 being the genes least tolerant of losing a copy. Missense variants: 1,048 observed, 1,253.7 expected, observed/expected ratio (o/e) 0.84, 90% interval 0.79 to 0.88. Synonymous variants: 471 observed, 490.59 expected, observed/expected ratio (o/e) 0.96, 90% interval 0.89 to 1.04.
Gene-disease validity (ClinGen):
ClinGen rates the evidence that CLCN2 causes each of these diseases.
epilepsy (autosomal dominant): Refuted. A brain disorder characterized by episodes of abnormally increased neuronal discharge resulting in transient episodes of sensory or motor neurological dysfunction, or psychic dysfunction.
Homologues: Orthologues: chimpanzee CLCN2 (99% identical), macaque CLCN2 (99% identical), pig CLCN2 (96% identical), dog CLCN2 (95% identical), rabbit CLCN2 (95% identical), mouse Clcn2 (94% identical), rat Clcn2 (94% identical), guinea pig CLCN2 (91% identical), tropical clawed frog clcn2 (73% identical), zebrafish clcn2b (72% identical), zebrafish clcn2a (71% identical), zebrafish clcn2c (45% identical), and 2 more. Paralogues in human: CLCN1 (51% identical), CLCNKA (35% identical), CLCNKB (34% identical), CLCN5 (23% identical), CLCN3 (22% identical), CLCN4 (22% identical), CLCN7 (21% identical), CLCN6 (20% identical).
Diseases named in the same sentence as CLCN2 in open-access papers:
CLCN2 is named in the same sentence as 83 diseases in open-access papers, as found by Europe PMC text mining. Sharing a sentence is not in itself a finding about the gene and the disease. The quoted sentences say what the papers report.
Leukoencephalopathy (22 papers, 2013 to 2026). This term describes abnormality of the white matter of the cerebrum resulting from damage to the myelin sheaths of nerve cells. "In humans, mutations in the ClC-2 gene have been associated with ClC-2 LD, also named CLCN2-related leukoencephalopathy." (PMID 41465860, 2025). "Mutations in the human CLCN2 gene, which encodes the ClC-2 chloride channel, were first found in a type of leukoencephalopathy with intramyelinic edema." (PMID 40683311, 2025). "Subsequently, a CLCN2 missense mutation was reported in a man showing infertility and subclinical leukoencephalopathy, as evidenced by the presence of azoospermia in semen analyses." (PMID 40683311, 2025). "In humans, loss-of-function mutations in the CLCN2 gene are associated with a subtype of the white matter disorder leukodystrophy, also known as CLCN2-related leukoencephalopathy, manifesting as intramyelinic edema in the brain and perhaps infertility." (PMID 34070744, 2021). "Loss-of-function mutations in the CLCN2 gene were recently discovered to be a cause of a type of leukodystrophy named CLCN2-related leukoencephalopathy (CC2L), which is characterized by intramyelinic edema." (PMID 31291907, 2019). "In humans, CLCN2 mutations have been associated with leukoencephalopathy." (PMID 40140900, 2025). "On the other hand, loss-of-function mutations in the CLCN2 gene have been linked to a type of leukodystrophy (white matter disorder), CLCN2-related leukoencephalopathy, characterized by intramyelinic edema in the brain, which is reminiscent of the myelin vacuolation found in ClC-2 knockout mice." (PMID 32466489, 2020). "Mutations in CLCN2 are responsible for leukoencephalopathy with ataxia." (PMID 33343406, 2020). "In addition to leukoencephalopathy, patients with mutations in CLCN2 or altered function of the channel also show cognitive impairment." (PMID 31479171, 2019). "Similarly, early work demonstrated that a homozygous ClC-2 mutation at nucleotide 1063 in CLCN2, which converts a glutamine to a stop codon, experiences leukoencephalopathy in multiple brain areas." (PMID 24378849, 2013). "Naturallyoccurring rare germline variants of the CLCN2 gene have beenreported in human populations, as detailed in European epilepsy cohorts, a Central African cohort, and they are also associatedwith leukoencephalopathy and familial hyperaldosteronism type II." (PMID 41196931, 2025). "Mutations in the CLCN2 gene predict to impair the stability of the protein, which reduces channel function and may contribute to intracellular chloride accumulation or neuronal hyperexcitability and results in CLCN2-related leukoencephalopathy." (PMID 36435927, 2023). "This study expands the genotypic spectrum of LKPAT, indicates the potential pathogenesis of the CLCN2 A506V variant, and provides valuable insights into further investigation into therapeutics of CLCN2-related leukoencephalopathy." (PMID 41822756, 2026). "In humans and mice, disruption of CLCN2 results in leukoencephalopathy, as well as retinal and testes degeneration." (PMID 40140900, 2025). "In this article, we report the third case of chloride voltage-gated channel 2 (CLCN2)-related leukoencephalopathy (CC2L) in Japan." (PMID 38975464, 2024). "The clinical and radiological features of II:1, II:2, and II:4 were well compatible with CLCN2-related leukoencephalopathy, and the MRI findings are extremely unusual and almost pathognomonic for this disorder." (PMID 36879630, 2023). "Indeed, mutations in genes encoding ion channels have been described in two LDs, the hypomyelinating HLD19 LD and the ClC-2 LD, also termed CLCN2-related leukoencephalopathy, caused by mutations in the TMEM63A and CLCN2 genes, respectively." (PMID 41465860, 2025). "Thus, some LDs are related to astrocytes misfunctioning, as in the case of MLC and CLCN2-related leukoencephalopathy." (PMID 41465860, 2025).
Leukoencephalopathy (continued). "Particular interest was placed on the CLCN2 gene due to its known association with neurological disorders such as leukoencephalopathy and epilepsy, despite the fact that its expression has not previously been reported in granulocytes." (PMID 40699858, 2025). "Nevertheless, our interpretation is that the specific and highly unusual MRI abnormalities in our patients very likely are associated with CLCN2-related leukoencephalopathy, and not with SPG56." (PMID 36879630, 2023). "Furthermore, we can confirm that male infertility is part of CLCN2-related leukoencephalopathy in humans and present the first testicular biopsy that shows that the mechanism behind the azoospermia is incomplete maturation arrest." (PMID 36879630, 2023). "Despite widespread CLCN2 expression, subjects with gain-of-function CLCN2 variants shared no apparent pathology other than PA, whereas loss-of-function CLCN2 variants caused slowly developing leukoencephalopathy with ataxia, blindness and male infertility." (PMID 34829937, 2021). "Interestingly, CLCN2 shows co-expression with TREM2 which, other than being an AD risk gene, is known to cause leukoencephalopathy in PLOSL (polycystic lipomembranous osteodysplasia with sclerosing leukoencephalopathy), also known as Nasu-Hakola disease." (PMID 29670507, 2018). "Infertility due to azoospermia has previously been described in two male patients with CLCN2-related leukoencephalopathy, but findings from testicular biopsy has not been reported so that the exact type of the azoospermia has remained unknown." (PMID 36879630, 2023).
epilepsy (17 papers, 2007 to 2025). "Previous studies in humans have suggested a potential link between CLCN2 mutations and epilepsy, particularly idiopathic generalised epilepsy (IGE) and focal epilepsy." (PMID 40223930, 2025). "The role of CLCN2 mutations in epilepsy appears to be nuanced, with these mutations possibly acting as susceptibility factors rather than direct causes." (PMID 40223930, 2025). "A polygenic heterogeneity model posits that although CLCN2 mutations can influence neuronal excitability, these changes likely lead to epilepsy only in conjunction with mutations in other genes." (PMID 40223930, 2025). "Research has indicated that the expression of CLCN2 in epilepsy-associated brain tissue is approximately 50% lower than that of controls, indicating a significant loss of functional ClC-2 channels." (PMID 40223930, 2025). "In humans, mutations in the ClCN2 gene predict hyperexcitability of GABAergic synapses, which can lead to epilepsy." (PMID 24378849, 2013). "The association of CLCN2 heterozygous variants with epilepsy remains unproved so far." (PMID 38173802, 2024). "Although there is some evidence linking CLCN2 mutations to susceptibility to epilepsy, these data remain controversial, and these cases could alternatively be explained by undetected digenic inheritance." (PMID 31780880, 2019). "Recent massive parallel sequencing for patients with sporadic epilepsy of unknown etiology identified SNVs in the chloride channel genes, CLCN1 and CLCN2, suggesting an association of CLCs with epilepsy." (PMID 25794116, 2015). "Therefore, we speculated that CLCN2 G161S might cause a neurodevelopmental dysfunction underlying epilepsy and GTS." (PMID 33343406, 2020). "Currently, mutations in the CLCN1, CLCN2, CLCN3, CLCN4, and CLCN6 genes have been reported to be associated with various forms of epilepsy." (PMID 40223930, 2025). "For example, the following genes were previously thought to be associated with epilepsy: EFHC1, SCN9A, CLCN2, GABRD, SRPX2 and CACNA1H." (PMID 28558813, 2017). "Some studies reported polymorphisms or mutations in the chloride channel genes CLCN2 (ClC-2) and CLCN1 (ClC-1) in epileptic patients but the involvement of these channels in epilepsy remains controversial." (PMID 27242528, 2016). "A subset of these genes has been implicated in other neurobehavioral disorders including depression (SLIT3), epilepsy (CLCN2, PRICKLE1), intellectual disability (AP4M1), schizophrenia (WDR60), and Tourette syndrome (OFCC1)." (PMID 24410847, 2014). "CACNB4, CLCN2, MAGI2, and SRPX2 variants have all been proposed as causes of epilepsy." (PMID 40492992, 2025). "One argument against the direct link between CLCN2 mutations and epilepsy is that these mutations do not follow a Mendelian inheritance pattern." (PMID 40223930, 2025). "CLC2-related disease shows similarities with MLC, albeit patients harboring mutations in CLCN2 genes do not experience epilepsy." (PMID 33328899, 2020). "Several other genes that we have identified as undergoing mTLE-linked alternative splicing events also have been associated with other, non-mTLE forms of human epilepsy, including CACNA1A, CACNA1H, CLCN2, and GABRG2, indicating that these also may be of particular interest in the epilepsy field." (PMID 17343748, 2007). "However, CLCN2 knockout mice do not exhibit spontaneous epilepsy or reduced seizure thresholds." (PMID 40223930, 2025).
leukodystrophy (11 papers, 2019 to 2025). Leukodystrophies are a group of rare, progressive, metabolic, genetic diseases that affect the brain, spinal cord and often the peripheral nerves. "Loss-of-function mutations in the ClC-2-encoding human CLCN2 gene are linked to the white matter disease leukodystrophy." (PMID 34070744, 2021). "Several years later, homozygous CLCN2 loss-of-function mutations were identified in patients with leukodystrophy, in some cases accompanied by visual problems or azoospermia-related infertility." (PMID 33187987, 2021). "Gain-of-function and loss-of-function mutations in the ClC-2-encoding human CLCN2 gene are linked to the genetic diseases aldosteronism and leukodystrophy, respectively." (PMID 32466489, 2020). "Previous biochemical analyses have revealed that leukodystrophy-causing CLCN2 mutations are associated with enhanced protein degeneration of ClC-2." (PMID 32466489, 2020). "Herein, we report a novel and pathogenic variant of CLCN2 in a woman with leukodystrophy and visual impairment." (PMID 31291907, 2019). "This underlines the limitation of panel sequencing, which unlike WES or WGS, does not allow for future re-analysis of DNA to detect for mutations in leukodystrophy genes that are discovered after initial panel curation (in this case the CLCN2, AARS, CTSA, and RNF216 genes)." (PMID 33597917, 2021). "In addition to altered voltage-dependent gating properties, leukodystrophy-causing CLCN2 mutations lead to defective human ClC-2 proteostasis, manifesting as impaired protein stability and membrane trafficking." (PMID 32466489, 2020). "Interestingly, consistent with the presence of testicular degeneration in Clcn2-deficient mice, infertility was observed in a leukodystrophy patient carrying a loss-of-function mutation in the CLCN2 gene." (PMID 32466489, 2020). "Herein, we report a novel mutation in CLCN2 in an individual with leukodystrophy." (PMID 31291907, 2019). "Hence, disruption of Clcn2 in astrocytes is insufficient to cause overt leukodystrophy." (PMID 33187987, 2021). "Loss of function mutations in CLCN2, initially thought to be implicated in MLC, are responsible for another form of leukodystrophy with a delay onset between 1 and 12 years." (PMID 40688418, 2025). "Specific Clcn2 disruption in astrocytes or oligodendrocytes produced no or only mild leukodystrophy, respectively, whereas the full extent of Clcn2-related leukodystrophy was reproduced by combined disruption in both cell types." (PMID 33187987, 2021). "Infertility associated with azoospermia has also been found in a male patient with subclinical CLCN2-related leukodystrophy." (PMID 33187987, 2021). "We explored the function of the Drosophila ClC‐a chloride channel, since its mammalian ortholog CLCN2 is expressed in glial cells, and defective channel function results in leukodystrophies, which in humans are accompanied by cognitive impairment." (PMID 31479171, 2019). "CLCN2-knockout mice display a leukodystrophy phenotype with extensive myelin vacuolization." (PMID 38975464, 2024). "Hence, Clcn2 needs to be disrupted in most or all cells of the oligodendrocyte–astrocyte syncytium to yield the full-blown leukodystrophy of Clcn2−/− mice." (PMID 33187987, 2021). "The presence of vacuoles in myelin sheaths of central neurons of Clcn2−/− mice suggests an oligodendrocyte-intrinsic role of ClC-2, but it has remained unclear whether other cell types contribute to CLCN2-related leukodystrophy." (PMID 33187987, 2021). "Oligodendrocyte-specific disruption of Clcn2 was sufficient to generate vacuoles in white matter but failed to fully reproduce the severity of Clcn2−/− leukodystrophy." (PMID 33187987, 2021).
Ataxia (9 papers, 2018 to 2026). Ataxia refers to impaired coordination of voluntary muscle movement. "Mutations in CLCN2 are a rare cause of autosomal recessive leucoencephalopathy with ataxia and specific imaging abnormalities." (PMID 38173802, 2024). "Mutations in CLCN2 have also been associated with cerebellar ataxia occurring during dystrophic leukoencephalopathy, a neurodevelopmental disorder characterized by cerebellar ataxia, spasticity, optic neuropathy, and chorioretinopathy with visual defects." (PMID 37631975, 2023). "Two siblings were previously reported with an overlap of SPG56- and CLCN2-associated leucoencephalopathy and ataxia, carrying biallelic pathogenic CYP2U1 variants and also biallelic CLCN2 likely pathogenic variants, with azoospermia and MRI compatible with CLCN2, suggesting a true overlap." (PMID 38173802, 2024). "Leukoencephalopathy with ataxia (LKPAT), also known as CLCN2-related leukoencephalopathy, is a rare autosomal recessive disorder caused by pathogenic variants in CLCN2, which encodes ClC-2, a ubiquitously expressed chloride channel protein." (PMID 41822756, 2026). "Despite the possibility that these psychiatric features are not related to CLCN2 in these patients, the presence of co-occurring ataxia, typical MRI findings and the absence of other variants associated with ASD on WES for one patient suggest that ASD may be part of the LKPAT disease spectrum." (PMID 38173802, 2024).
Infertility (7 papers, 2020 to 2026). "Both male CLCN2 carriers were infertile, and review of the literature revealed one reported case with azoospermia, however the brother had no overt signs of SPG56." (PMID 36879630, 2023).